PTH (parathyroid hormone)
Diseases named in the same sentence as PTH in open-access papers (continued):
Sharing a sentence is not in itself a finding about the gene and the disease.
hypertriglyceridemia (7 papers, 2016 to 2025). A laboratory test result indicating elevated triglyceride concentration in the blood. "Intravenous 1,25(OH)2D3 improved glucose metabolism and hypertriglyceridemia in hemodialysis patients independent of PTH suppression." (PMID 40906132, 2025).
Hypoglycemia (7 papers, 2015 to 2026). A decreased concentration of glucose in the blood. "A comparison of the general data between the NDPN and DPN groups revealed statistically significant differences in BMI, RHR, TG, FT3, BUN, 25(OH)D3, total 25(OH)D (p < 0.05), sex, age, HBP, hypoglycemia, HbA1c, P, Ca, TC, HDL-C, LDL-C, TSH, FT4, PTH, fasting C-peptide, and UA (p > 0.05)." (PMID 40551892, 2025). "Following hypoglycemia, transient changes from baseline occurred in DKK1, cathepsin A, cathepsin G, cathepsin H, cathepsin S, cathepsin Z, parathyroid hormone (PTH), Sphingosine kinase 1 and 2 (SPK1/2), and interleukin-1 beta (IL1 beta) over the post-hypoglycaemia time course." (PMID 41373586, 2025).
neuropathy (7 papers, 2005 to 2025). A disorder affecting the nervous system that manifests with pain, tingling, numbness, and/or muscle weakness. "Some relevant clinical and laboratory parameters (age, sex, xerosis, presence of neuropathy, duration of dialysis, history of atopy and laboratory findings including hematocrit, creatinine, urea, calcium, phosphorus, parathyroid hormone [PTH] and alkaline phosphatase) were evaluated." (PMID 15975150, 2005). "Several potential hypotheses have been formulated to explain the increased risk of atopic dermatitis in CKD patients, including endogenous opioid system imbalance, alternation of immune status, neuropathy, functional and structural changes in the brain, and parathyroid hormone abnormalities." (PMID 37441684, 2023).
Parkinson disease (7 papers, 2021 to 2025). A progressive degenerative disorder of the central nervous system characterized by loss of dopamine producing neurons in the substantia nigra and the presence of Lewy bodies in the substantia nigra and locus coeruleus. "Besides ER, other hormones such as PTH and vitamin D also play important roles in the bone metabolism process of Parkinson’s patients." (PMID 39684552, 2024).
progressive osseous heteroplasia (7 papers, 2009 to 2024). A rare genetic bone disorder characterized clinically by progressive extraskeletal bone formation presenting in early life with cutaneous ossification, that progressively involves subcutaneous and then subsequently deep connective tissues, including muscle and fascia. "The diagnosis of osteoma cutis, nodules of subcutaneous ossifications or deep heterotopic ossifications should trigger a clinical and biochemical work-up to search for signs of AHO, PTH and TSH resistance or FOP, especially if the first digit of both feet is abnormal." (PMID 29959430, 2018). "Progressive osseous heteroplasia (POH) describes the condition presenting superficial ossifications progressing into deep connective tissue, with two or fewer AHO features and no PTH resistance." (PMID 33179219, 2021).
aortic valve calcification (6 papers, 2011 to 2025). "Although it has been reported that aortic valve calcification was positively associated with PTH, the pathophysiological mechanisms and the direct effects of PTH on human valvular cells remain unclear." (PMID 35409134, 2022). "Since ageing and atherosclerosis—factors associated with valvular calcification—are present in only 50% of patients with severe aortic stenosis, discovering if aortic valve calcification is associated with PTH levels may provide important insights into the pathogenesis of CAVD." (PMID 35409134, 2022). "Therefore, evaluation of the levels of serum PTH and 1,25-dihydroxy vitamin D, early markers for impaired mineral metabolism, is important to clarify the underlying mechanisms that are responsible for the progression of calcific aortic valve disease in early stage CKD." (PMID 22087774, 2011). "Increased levels of PTH were found to correlate with the progression of the aortic valve calcification process and with extended calcification area of the aortic valve, but the precise role of this hormone in calcific aortic valve disease (CAVD) is unclear." (PMID 35409134, 2022).
autosomal dominant hypocalcemia (6 papers, 2013 to 2023). Autosomal dominant hypocalcemia (AD hypocalcemia) is a disorder of calcium homeostasis characterized by variable degrees of hypocalcemia with abnormally low levels of parathyroid hormone (PTH) and persistent normal or elevated calciuria. "In humans, gain-of-function mutations of the calcium-sensing receptor (CASR) gene are the cause of autosomal dominant hypocalcemia or type 5 Bartter syndrome characterized by an abnormality of calcium metabolism with low parathyroid hormone levels and excessive renal calcium excretion." (PMID 24244430, 2013). "Conversely, CaSR gain-of-function mutations cause autosomal dominant hypocalcemia (ADH) or type 5 Bartter syndrome, due to activation of the receptor at concentrations of serum calcium below physiological levels leading to abnormal inhibition of PTH secretion." (PMID 24244430, 2013). "T888M was identified previously in a human kindred with autosomal dominant hypocalcemia (ADH) providing evidence that phosphorylation of T888 impairs 1) sustained elevations in Ca2+i and 2) CaSR-mediated suppression of PTH secretion." (PMID 36818436, 2023). "Autosomal dominant hypocalcemia (ADH1) is a genetic disorder characterized by low serum calcium and low or inappropriately normal levels of parathyroid hormone." (PMID 37654565, 2023).
Bartter syndrome (6 papers, 2013 to 2023). "Small cohort studies have reported high parathyroid hormone (PTH) levels in patients with Bartter syndrome and lower serum phosphate levels have anecdotally been reported in patients with Gitelman syndrome." (PMID 35137195, 2022). "Treatment of Bartter syndrome patients with NSAIDs reduces renal calcium excretion and in one report, reduces PTH levels." (PMID 35137195, 2022). "Overall, patients included in the NOS subgroup tended to resemble more patients with type I and II Bartter syndrome, especially if they had elevated PTH." (PMID 35137195, 2022). "In conclusion, this cross-sectional study demonstrates that PTH is frequently elevated in patients with Bartter syndrome, especially in those with type I and II disease." (PMID 35137195, 2022).
benign parathyroid tumors (6 papers, 2012 to 2025). "The serum Ca and PTH levels in patients with MEN1-PC/APN are usually greater than in those with MEN1-associated benign parathyroid tumors." (PMID 33101196, 2020). "Patients with PC usually present with serum calcium greater than 14 mg/dL, which is higher than that in patients with benign parathyroid tumors and a parathyroid hormone (PTH) level at least twice the upper limit of normal." (PMID 34135961, 2021).
coronary artery calcification (6 papers, 2015 to 2025). Calcification of the coronary artery, used as a measure of coronary atherosclerosis, a risk factor for myocardial infarction. "Elevated serum calcium, phosphorus, and parathyroid hormone (PTH) are all independently linked to increased risk of coronary artery calcification and carotid intima media thickness (CIMT) in children with chronic KF." (PMID 36114889, 2023). "However, while there is a consistent association between chronic kidney disease and a higher burden of coronary artery calcification, the associations among phosphorus, calcium, and parathyroid hormone with coronary artery calcification in these patients is inconsistent." (PMID 37233177, 2023).
Fanconi syndrome (6 papers, 2012 to 2025). "Renal causes can be divided into intrinsic renal causes (e.g., Fanconi syndrome), parathyroid hormone-dependent causes (e.g., calcipenic rickets), and fibroblast growth factor 23-dependent causes (e.g., X-linked hypophosphatemia)." (PMID 41008628, 2025). "Patients with Fanconi’s syndrome show low phosphate levels (because of renal phosphate loss) and normal levels of calcium, 25-hydroxyvitamin D, 1,25-dihydroxyvitamin D, and PTH and increased ALP levels." (PMID 22906214, 2012). "Furthermore, several case reports of tenofovir-associated Fanconi syndrome have reported that the majority of these cases had normal 25(OH)D and PTH levels, further supporting this theory." (PMID 22984574, 2012). "Surprisingly, we observed a dramatic improvement in laboratory parameters within two weeks from the treatment initiation, including normalisation of phosphate and PTH concentrations and resolution of Fanconi syndrome, prompting discontinuation of phosphate supplements." (PMID 40225330, 2025). "However, there was a tendency towards low parathyroid hormone (PTH) and low fibroblast growth factor 23 (FGF23) levels, likely reflecting the consequences of chronic tubular phosphate wasting, although Fanconi syndrome appeared to be well controlled in these patients." (PMID 35011732, 2022).
gout (6 papers, 2012 to 2025). A condition characterized by painful swelling of the joints, which is caused by deposition of urate crystals. "We also uncovered a very strong independent association between elevated PTH and the occurrence of gout." (PMID 30682034, 2019). "From univariate linear regression analysis, the factors associated with BMD of the total spine were female, BMI, ischemic stroke, gout, ACEi use, PTH > 585 pg/mL, and ALP > 120 U/L." (PMID 36676753, 2023). "Regardless, confirming the relation in a prospective longitudinal observational context (for example, the relation between prior PTH levels and incident gout, particularly in a renally impaired group) would be valuable." (PMID 22405053, 2012). "Indeed in our analysis, a rising serum PTH level was a stronger correlate of gout than worsening eGFR, suggesting a strong pathobiological basis." (PMID 30682034, 2019). "Gout patients also experienced significantly lower serum albumin concentrations and significantly higher parathyroid hormone concentrations than those without gout, all p<0.001." (PMID 30682034, 2019).
human papillomavirus infection (6 papers, 2020 to 2025). "KEGG pathway enrichment analysis indicated that DE RNAs in KBD were associated with various pathways such as adherens junction, TGF-β signaling pathway, parathyroid hormone synthesis, secretion and action, human papillomavirus infection, and osteoclast differentiation." (PMID 38673933, 2024). "In addition, KEGG analysis revealed that these genes primarily focused on parathyroid hormone synthesis, secretion, action, human papillomavirus infection, and the P13K-AKT signaling pathway." (PMID 36685841, 2022). "The KEGG pathway analysis showed that these genes were mainly enriched in parathyroid hormone synthesis, secretion, action, human papillomavirus infection, and the P13K-AKT signaling pathway, suggesting that these pathways might be closely related to BMD and OP." (PMID 36685841, 2022).
infertile (6 papers, 2018 to 2025). "In this study, a 3-month supplementation with 4000 IU/day VD3 significantly increased serum 25(OH) VD3, PTH, phosphorus, and seminal and serum calcium; T/LH ratio; and total and progressive sperm motilities in infertile men with asthenozoospermia." (PMID 34225767, 2021). "As with Vdr (R270L) rats, administration of 25(OH)D3 exerted pronounced effects on Cyp27b1-KO rats, resulting in normalization of plasma calcium and PTH levels, osteogenesis, and infertility in females." (PMID 32231239, 2020). "The efficacy of ovulation induction through letrozole 2.5 mg for five days in infertile, anovulatory PCOS women is associated with lower serum AMH levels, whereas parameters of calcium metabolism, such as serum calcium, 25OHD3, and PTH do not seem to be predictive." (PMID 35566720, 2022). "Additionally, the work of other authors has shown that a deficiency in vitamin D can lead to an increase in the parathyroid hormone, which is accompanied by PCOS, infertility due to lack of ovulation, and high testosterone levels." (PMID 30423869, 2018). "The study was conducted on a small cohort as far as subgrouping of infertile subjects in which lifestyle influences, the status of smoking, screening by DNA Fragmentation Index (DFI), calcium and phosphorus levels, and Parathyroid hormone status were not estimated." (PMID 30386296, 2018).
ischemic stroke (6 papers, 2014 to 2023). A stroke disorder caused by obstruction of blood flow to the brain, due to thrombotic (local blood clot formation) or embolic (due to a blood clot or other material traveling from another site) event. "A longitudinal study of HD patients in the Japan Renal Data Registry found that hemorrhagic stroke was associated with PTH concentration > 500 pg/ml, whereas the incidence of ischemic stroke was unrelated to PTH level." (PMID 31830923, 2019). "Our major findings were that among the 3 end points of MI, hemorrhagic stroke, and ischemic stroke, P, cCa, and intact PTH levels had the greatest associations with incident MI." (PMID 25494334, 2014). "In this study, the associations between P, cCa, and intact PTH levels, and various cardiovascular diseases (MI, hemorrhagic stroke, and ischemic stroke) were examined separately." (PMID 25494334, 2014). "In recent years, many studies have been done on the role of thyroid hormone, growth hormone, testosterone, prolactin, oxytocin, glucocorticoid, parathyroid hormone, and dopamine in ischemic stroke, but comprehensive reviews are scarce." (PMID 36569944, 2022). "The present investigation explores a new concept of mobilizing endogenous stem cells/progenitor cells from the bone marrow using a parathyroid hormone (PTH) therapy after ischemic stroke in adult mice." (PMID 24503654, 2014). "Mobilizing endogenous bone marrow-derived stem cells/progenitor cells using PTH and other mobilizers appears an effective and feasible regenerative treatment after ischemic stroke." (PMID 24503654, 2014). "Our data suggests that PTH therapy improves endogenous repair mechanisms after ischemic stroke with functional benefits." (PMID 24503654, 2014). "We suggest that the PTH-mobilized ESCs/EPCs from the bone marrow and the functional benefits represent a new potential regenerative therapy for tissue repair after ischemic stroke." (PMID 24503654, 2014). "Based on this available information, we decided to test PTH as a bone marrow cell mobilizer and its regenerative potential after ischemic stroke." (PMID 24503654, 2014). "Nevertheless, if PTH does have a direct action in the brain, our investigation still suggests a new therapy of using PTH in regenerative treatment after ischemic stroke." (PMID 24503654, 2014). "More research is required on parathyroid hormone and ischemic stroke." (PMID 36569944, 2022). "It has not been tested whether PTH is neuroprotective in vivo after ischemic stroke." (PMID 24503654, 2014).
lung carcinoma (6 papers, 2012 to 2024). "PTHrP was purified from a human lung cancer cell line, and was shown to have biological activities similar to parathyroid hormone (PTH)." (PMID 23588777, 2013). "For example, Runx2 interaction with p300 alters chromatin structure (acetylation of histones H3 and H4) during activation of MMP-13 gene in bone cell lineage in response to PTH and enhances histone acetylation resulting in increased Snail expression and decreased E-cadherin in lung cancer cells." (PMID 22537242, 2012). "The medium contains the osteoblast markers alkaline phosphatase, runt-related transcription factor 2, parathyroid hormone/parathyroid hormone–related peptide receptor, and type I collagen and osteocalcin, which could produce paracrine effectors of lung cancer growth into the bone." (PMID 27042161, 2016). "This study focuses on evaluating serum parathyroid hormone (PTH), C-reactive protein (CRP), lipid profile parameters, and interleukin-6 (IL-6) in relation to the stages of lung cancer, exploring their potential as biomarkers for assessing disease severity." (PMID 39816276, 2024). "The study revealed that PTH, CRP, IL-6, and lipid profile parameters play a significant role as markers of lung cancer progression." (PMID 39816276, 2024). "The primary objective of this study was to evaluate and compare the serum levels of PTH, CRP, lipid profile parameters, and IL-6 across different stages of lung cancer." (PMID 39816276, 2024). "Ectopic production of a variety of hormones such as ADH, parathyroid hormone, ACTH, insulin-like growth factor, thus leading to presentation as endocrine syndromes in patients with lung cancer are well known." (PMID 33394143, 2021). "Similar results were obtained with other PTH–nonexpressing cells such as human breast cancer MCF7 and human lung cancer A549." (PMID 35618021, 2022).
ovarian carcinoma (6 papers, 2016 to 2025). A malignant neoplasm originating from the surface ovarian epithelium. "In an ovarian carcinoma the expression was linked to rearrangement of the PTH gene, while in a case of high-grade neuroendocrine carcinoma of the pancreas, ectopic PTH expression was associated with hypomethylation of the PTH locus." (PMID 40641561, 2025). "One underlying explanation for our findings is that a higher level of calcium might be inversely related to ovarian cancer risk via down-regulation of circulating parathyroid hormone (PTH)." (PMID 28665326, 2017). "Prior reports describe cases of intact PTH production from an ovarian carcinoma, neuroendocrine tumor, and small cell lung carcinoma." (PMID 39611185, 2024).
peripheral vascular disease (6 papers, 2016 to 2024). Any disorder affecting blood flow through the veins or arteries outside of the heart. "In univariable Cox regression analysis, dialysis technique, Geriatric Nutritional Risk Index, peripheral vascular disease, and intact parathyroid hormone and total calcium serum levels were significantly associated with baseline alkaline phosphatase serum levels." (PMID 38913269, 2024). "The ectopic vascular calcification by high i-PTH concentrations contributes to the manifestation of peripheral vascular disease in dialysis patients and to disorders in cardiac function." (PMID 28933414, 2016).
polycystic ovary syndrome (6 papers, 2015 to 2025). A disorder that manifests as multiple cysts on the ovaries. "Studies have reported that altered expression levels of PTH and PTH2R genes may be associated with ovarian disorders, such as elevated serum parathyroid hormone concentrations in polycystic ovary syndrome patients." (PMID 41154849, 2025). "Furthermore, Dimitrios indicated that calcium and vitamin D intake suppresses parathyroid hormone production, potentially improving hyperandrogenemia and anovulation associated with polycystic ovary syndrome (PCOS), thereby enhancing the chances of conception." (PMID 39968392, 2025). "Vitamin D and insulin play an important role in susceptibility to polycystic ovary syndrome (PCOS), and therefore vitamin D receptor (VDR), parathyroid hormone (PTH), and insulin receptor (INSR) gene variants might be involved in the pathogenesis of PCOS." (PMID 27141540, 2015).